PRR5L (proline rich 5 like)
Description:
Associates with the mTORC2 complex that regulates cellular processes including survival and organization of the cytoskeleton. Regulates the activity of the mTORC2 complex in a substrate-specific manner preventing for instance the specific phosphorylation of PKCs and thereby controlling cell migration. Plays a role in the stimulation of ZFP36-mediated mRNA decay of several ZFP36-associated mRNAs, such as TNF and GM-CSF, in response to stress. Required for ZFP36 localization to cytoplasmic stress granule (SG) and P-body (PB) in response to stress.
Synonyms: Protor-2; PROTOR2; FLJ14213
Tractability: PROTAC: UniProt records ubiquitination sites on it; ubiquitination databases record sites on it.
Gene: Protein-coding gene on chromosome 11 (36,296,120 to 36,465,209, forward strand). Ensembl gene ENSG00000135362.
Subcellular location (Human Protein Atlas): Cytokinetic bridge; Cytosol
Gene Ontology:
Molecular function: protein binding; ubiquitin protein ligase binding
Biological process: cellular response to oxidative stress; negative regulation of protein phosphorylation; positive regulation of intracellular protein transport; positive regulation of mRNA catabolic process; regulation of fibroblast migration; TORC2 signaling
Cellular component: TORC2 complex
Genetic constraint (gnomAD): Loss-of-function variants: 17 observed, 33.21 expected, observed/expected ratio (o/e) 0.51, 90% interval 0.35 to 0.77. The upper end of that interval is the gene's LOEUF score, 0.77, which puts it in group 3 of 6, group 1 being the genes least tolerant of losing a copy. Missense variants: 360 observed, 439.63 expected, observed/expected ratio (o/e) 0.82, 90% interval 0.75 to 0.89. Synonymous variants: 181 observed, 185.11 expected, observed/expected ratio (o/e) 0.98, 90% interval 0.87 to 1.11.
Homologues: Orthologues: chimpanzee PRR5L (99% identical), macaque PRR5L (98% identical), rabbit PRR5L (94% identical), mouse Prr5l (92% identical), guinea pig PRR5L (91% identical), rat Prr5l (90% identical), dog PRR5L (87% identical), pig PRR5L (72% identical), tropical clawed frog prr5l (65% identical), zebrafish prr5l (50% identical), zebrafish si:dkey-56p7.10 (29% identical). Paralogues in human: PRR5 (38% identical).
Diseases named in the same sentence as PRR5L in open-access papers:
PRR5L is named in the same sentence as 20 diseases in open-access papers, as found by Europe PMC text mining. Sharing a sentence is not in itself a finding about the gene and the disease. The quoted sentences say what the papers report.
celiac disease (2 papers, 2015 to 2021). An autoimmune genetic disorder with an unknown pattern of inheritance that primarily affects the digestive tract. "In the analyses comparing SNP alleles with celiac disease status (data not shown), the PRR5L intronic SNP rs10501156 was associated with celiac disease." (PMID 26123480, 2015).
Obesity (2 papers, 2018 to 2024). Accumulation of substantial excess body fat. "PRR5L expression was found differential in visceral adipose tissue of obesity patients and found to be required for efficient mTORC2-mediated activation of SGK1 (serum/glucocorticoid regulated kinase 1)." (PMID 38483771, 2024). "Among the genes affiliated with the 119 significant CpGs, SOCS3 and DOK2 were differentially expressed in the SAT of obesity patients, while seven genes (SOCS3, PRR5L, ABCG1, BRDT, B3GNT7, ZNF710, and RARRES1) were differentially expressed in the VAT of obesity patients." (PMID 30619480, 2018).
osteoarthritis (2 papers, 2017 to 2020). A noninflammatory degenerative joint disease occurring chiefly in older persons, characterized by degeneration of the articular cartilage, hypertrophy of bone at the margins and changes in the synovial membrane. "This link between PRR5L, TTP, and TNFα is interesting in light of recent studies demonstrating the association of a SNP (rs4755450) in PRR5L with juvenile idiopathic arthritis, and a microarray study showing that down-regulation of PRR5L was associated with osteoarthritis in adults." (PMID 27539829, 2017). "The gene with the second largest magnitude of negative association with methylation at birth, PRR5L, has been linked in GWAS to allergic diseases, found downregulated (expression) in osteoarthritis, and differentially methylated in type II diabetes." (PMID 32114984, 2020).
Sepsis (1 paper, 2021). Sepsis is defined as life-threatening organ dysfunction caused by a dysregulated host response to infection. "AKT1, top up- (FKBP5, SORT1, VNN1, and CST7) and downregulated (PRR5L, SH2B3, SULF2, PLEKHO1, and PTPN6) genes in sepsis were validated using RT-PCR." (PMID 33959663, 2021).
cancer (2 papers, 2017 to 2021). A tumor composed of atypical neoplastic, often pleomorphic cells that invade other tissues. "With the exception of TOR1AIP1 and PRR5L, almost all other hub genes have been reported to be involved in cancers." (PMID 33987007, 2021). "Genistein affects mTOR signaling, leading to increased interest in its use in cancer prevention and treatment, but epigenetic modification of PRR5L has not been previously reported." (PMID 27539829, 2017).
PRR5L also shares sentences with these, for which no sentence is quoted: asthma (2 papers); psoriasis (2); allergic disease (1); alopecia areata (1); autoimmune disease (1); inflammatory bowel disease (1); juvenile idiopathic arthritis (1); multiple sclerosis (1); Pancreatic Cancer (1); pancreatic tumor (1); rheumatoid arthritis (1); systemic lupus erythematosus (1); tumor (1); type II diabetes (1); type-I diabetes (1).